LINC00705 (long independently transcribed non-coding RNA 705)
Gene: Long non-coding RNA gene on chromosome 10 (4,655,348 to 4,682,722, forward strand). Ensembl gene ENSG00000225269.
Diseases named in the same sentence as LINC00705 in open-access papers:
LINC00705 is named in the same sentence as 1 disease in open-access papers, as found by Europe PMC text mining. Sharing a sentence is not in itself a finding about the gene and the disease.
LINC00705 shares sentences with these, for which no sentence is quoted: breast carcinoma (1 paper).